CDK6 (cyclin dependent kinase 6)
Diseases named in the same sentence as CDK6 in open-access papers (continued):
Sharing a sentence is not in itself a finding about the gene and the disease.
tumor (continued). "These concerns have been fuelled by RNA interference and knockout mice studies, indicating that functional redundancy may exist between different Cdks, with the loss of Cdk2 alone failing to inhibit tumour cell proliferation, and the loss of both Cdk4 and Cdk6 not preventing cell cycling." (PMID 17179992, 2007). "Analysis of the Pan-Cancer dataset integrating International Cancer Genome Consortium (ICGC) and The Cancer Genome Atlas (TCGA) further revealed a significant correlation between FRA1 levels and AXL, CDK6, and FSCN1 expression in 1210 tumor samples of all cancer types." (PMID 41286309, 2025). "As a pivotal component of the cyclin D-CDK4/6-Rb signaling pathway, CDK6 directly phosphorylates PFKP at S679 and PKM2 at S37, thereby increasing pentose phosphate metabolism and serine metabolism in tumor cells, elevating intracellular NADPH levels, and promoting tumor cell growth." (PMID 39980052, 2025). "The results reveal that CDK4 and CDK6—cyclin-dependent kinases that promote cell cycle progression—are significantly overexpressed in GBM brain samples, underscoring their role in tumor proliferation and identifying them as critical targets for miR-124 intervention." (PMID 40134003, 2025). "GNE-6776 significantly inhibited tumor growth without affecting body weight, reduced expression of CDK6, C-myc, and N-cadherin, and increased GSK3β expression in tumor tissue." (PMID 40006058, 2025). "Firstly, in the TCGA pan-cancer analysis, CDK6 was relatively highly expressed in several normal tissues compared to tumor tissues in types such as BRCA, KICH, KIRC, LUAD, THCA, and UCEC, suggesting a potential limitation in its tumor specificity." (PMID 40564887, 2025). "First, we investigated the correlation between CDK6 and p-ERK staining intensity levels in baseline tumor samples and PFS, as in our initial study we found that the tumor models with higher activity of those signaling nodes were the most sensitive to the combination." (PMID 40928353, 2025). "Combined with the clinical correlation analysis, we hypothesized that neferine may affect the cell cycle of GC through FLT3, CDK6, and SYK to generate an anti-tumor effect." (PMID 40138292, 2025). "Motivated by the previous findings, we conducted a phase IB clinical trial in patients with advanced TNBC that showed hyperactivation of CDK6 and/or MEK in their tumor samples, aiming to study a potentially powerful, orally available drug combination and biomarkers for this disease." (PMID 40928353, 2025). "The study demonstrated that EC could be one of the sensitive tumor types, as CDK4 was shown to have higher expression compared to CDK6 in various reproductive organ systems, where abemaciclib has a higher potency against CDK4 compared to CDK6." (PMID 39330025, 2024). "The cyclin-dependent kinase 6 (CDK6), in complex with cyclin D, regulates the progression of the cell cycle from G1 phase to S phase by phosphorylating the RB protein, which is critical for tumour cell survival and growth." (PMID 38212482, 2024). "CDK6 is a proliferative checkpoint pathway that is not exclusive to tumor cells but is also employed by immune cells." (PMID 37715207, 2023). "However, CDKN2B, also known as p15, is another critical tumor suppressor, which inhibits cyclin kinases CDK4 and CDK6." (PMID 36952446, 2023). "We observed increased 5hmC levels in H3K4me3 regions in genes relating to cell proliferation, such as CDK6 and ZMYND8, and reduced 5hmC levels in H3K4me3 regions in genes that may be related to tumor suppression, such as ARHGAP26 and GLI3." (PMID 37372359, 2023). "The authors found that the cell cycle kinase CDK6 forms an active complex with the atypical cyclin I (CCNI) and that this complex promotes retinoblastoma phosphorylation, E2F‐mediated gene expression, and tumor proliferation in vitro and in vivo, similarly to the cyclin D1 (CCND1)/CDK6 complex." (PMID 37081792, 2023).
tumor (continued). "Successful establishment of lenvatinib-resistant PLC/PRF/5 cells was confirmed by the observation that lenvatinib failed to suppress tumor growth, accompanied with high CDK6 expression." (PMID 37872167, 2023). "Moreover, inactivation of STING in Cdk4−/− and Cdk6−/− cancer cells reversed the hyper-activation of type I IFN response and the anti-tumor effect of Cdk4/6 knockout." (PMID 37833461, 2023). "We have provided evidence that either Cdk4 or Cdk6 knockout triggers DNA damage of cancer cells and retards tumor growth in vivo through activation of STING-dependent type I interferon induction pathway and anti-tumor immune responses." (PMID 37833461, 2023). "At the same time, we stained cell cycle pathway-related molecules in tumor tissues, and the results showed that compared with the control groups, the staining of p21 and p27 was stronger, while the staining of CDK4 and CDK6 was weaker in the bortezomib-treated groups." (PMID 37864031, 2023). "Although we have not studied the role of type III IFN in Cdk4−/− and Cdk6−/− tumor growth, we have transplanted Cdk4−/− and Cdk6−/− cancer cells into Ifnar1−/− mice." (PMID 37833461, 2023). "Tumors with low levels of CDK6 compared to CDK4 are universally sensitive to CDK4/6 inhibitors, including HR+ breast, mantle cell lymphomas, Ewing sarcomas as well as subsets of large tumor types, e.g. NSCLC." (PMID 36051751, 2022). "Therefore, inhibition of CDK6 by palbociclib results in activation of PFKP and PKM2, depletion of NADPH and glutathione, increase in ROS, and apoptosis of tumor cells." (PMID 35327487, 2022). "Disruption of ccnd loci and that of cdk4 (but not cdk6) in MEFs, as well as treatment of tumor cell lines with CDK4 inhibitors, also stabilize PD-L1 at the protein level." (PMID 36051751, 2022). "23.7% of primary tumours were CDK4 positive and 44.8% were CDK6 high." (PMID 34921235, 2022). "In total, between 20.0% and 23.3% of the tumours are Rbpositive/p16negative, Rbpositive/CDK4positive, or Rbpositive/CDK6high, which corresponds to the group of patients that might benefit from CDK4/CDK6 inhibitor treatment." (PMID 34921235, 2022). "The tumor suppressor effect of miR-124 was also observed through the inhibition of cell cycle-related cyclin D1, cyclin-dependent kinase 2 (CDK2), cyclin-dependent kinase 4 (CDK4), and cyclin-dependent kinase 6 (CDK6)." (PMID 35326471, 2022). "In tumour without CDK6 amplification, the resistant cancer cell state was deemed to reflect a phenotypic shift from ERK to JNK MAPK signalling and reduced oestrogen signalling." (PMID 35800379, 2022). "Tumor-normal and inter-tumor analyses of protein expression data highlighted multiple aberrantly-expressed protein targets in key signaling pathways, including PDGFRB, CDK6, ERBB2, and EGFR whose protein overexpression in HCC tumors are also validated by IHC data from the Human Pathology Atlas." (PMID 35433463, 2022). "In addition, the lncRNA Neat1 was reported to regulate CDK6 and CDK14 via sponging miR107 and further promote tumor growth." (PMID 35501920, 2022). "Meanwhile, some scientists have proposed that the anti-tumor mechanism of Tetrastigma hemsleyanum may include calcium signaling pathway, PI3K/AKT/mTOR signaling pathway and CDK6 and MET genes." (PMID 36389762, 2022). "As CDK6 may be important in the development of PCa and EnzR CRPC, we collected PCa tumor tissues and para-cancerous tissues and EnzR PCa cell lines to compare the CDK6 expression among them." (PMID 35780240, 2022).
tumor (continued). "When combination therapy was used in tumour without CDK6 amplification, JNK activation provided an alternative pathway to oestrogen-independent cell proliferation." (PMID 35800379, 2022). "Furthermore, some oncogenic genes like EGFR, CDK6, YAP1, and MMP7 were amplified in the TP53INP2-low patients while some tumor suppressor genes including CDKN2A, KLF6, and PTEN were deleted." (PMID 33897760, 2021). "Key kinases regulating cell cycle G1 progression were also altered in different CTC samples including cyclin-dependent kinase 6 (CDK6, chr7) gain in CTC 1 of P43 and in single CTCs of P50, and cyclin-dependent kinase 4 (CDK4, chr12) gains in 5/7 CTCs of P45 and the corresponding tumor biopsy." (PMID 34272470, 2021). "GAS5 was confirmed to inhibit tumour cell proliferation and promote cell apoptosis, and these processes were modified by cyclin-dependent kinase 6 (CDK6), which had a negative correlation with GAS5 in BCa progression." (PMID 33968736, 2021). "Notably, tumor sample analysis showed that RB1 protein abundance was slightly increased, while protein levels of CDK6, cyclin D3, cyclin E1, cyclin D1, SKP2, and CDK2 were significantly decreased in the combination treatment group." (PMID 34508104, 2021). "The main molecular mechanisms of miR-34a-mediated tumor suppression included, but were not limited to repressing cell proliferation (c-MYC, E2F, CDK4, and CDK6), promoting cell apoptosis (Bcl2, SITR1, and AXL), and inhibition of cell invasion and metastasis (c-MET, SNAIL, MMP9, CD44, and NOTCH1)." (PMID 33796457, 2021). "However, in line with the multiple activities of CDK4 and CDK6, it is highly expected that the use and the success of CDK4/6i will be also related to many other alterations, present both in tumor cells and in tumor microenvironment." (PMID 34204543, 2021). "Taken together, these findings unveiled a tumor-suppressive role of CDC37L1 in GC, and CDK6 may act as a downstream effector in this process." (PMID 33976724, 2021). "Interestingly, we observed that GBM-N019 synergized with palbociclib and significantly delayed tumor growth with concomitant suppression of p-mTOR, mTORC1, mTORC2, Akt, NF-κB, STAT3, and CDK6 when compared to individual therapies." (PMID 34572040, 2021). "However, GBM-N019-targeted mTOR/CDK6/STAT3 signature, supported by a wealth of literature, contributes to tumor progressions, stemness, distant metastasis, and regulation of immune checkpoint blockade therapy outcome." (PMID 34572040, 2021). "While knockdown of CDK6, ZEB1, and Sec23a expression compromised mammosphere formation, tumor cell migration, and/or clustering of MDA-MB-231 cells, only siCDK6 partially mimicked siICAM1 in inhibiting lung colonization of MDA-MB-231 cancer cells within 7 days after tail vein injection." (PMID 34381029, 2021). "Consistent with the results of in vitro experiments, miR-30b-3p overexpression could promote tumor progression by decreasing RHOB and increasing Ki-67, CDK2, and CDK6." (PMID 33408780, 2021). "Cyclin-dependent kinase 6 (CDK6) was also transcriptionally activated by copy number amplification, which suggests the role of genomic copy number variation in the out-of-control cell cycle and tumor progression of PAs." (PMID 33472173, 2020). "mRNA expression levels of CDK4 and CDK6 were overexpressed in CCA tumor samples when compared to normal samples." (PMID 33116269, 2020). "CDK6 was not only known to be a cell-cycle kinase but also has a unique role of directly regulating transcription factors, which include AP-1 and vascular endothelial growth factor (VEGF-A), promoting tumor angiogenesis." (PMID 33597968, 2020). "Specifically, miR-641 was identified as a tumor suppressor in NSCLC, and researchers found that miR-641 inhibited NSCLC progression by targeting murine double minute 2 (MDM2) and cyclin-dependent kinase 6 (CDK6), respectively." (PMID 32655321, 2020).
tumor (continued). "Abnormal Rb regulation in tumor cells manifested with overexpressed CDK4/CDK6 and the loss of p16 expression or CDK4/CDK6 mutation leading to no response to p16." (PMID 32860670, 2020). "In addition, immunochemistry results showed that over-expression of ASB16-AS1 reduced the levels of CDK6 and IGF1R in xenografted tumor tissues." (PMID 33219221, 2020). "In our study, based on the ceRNA hypothesis, tumor-promoting genes, including KCNQ1OT1, JARID2, CDK6, DNMT3A, and TET1, competitively bound the tumor suppressor gene hsa-29c-3p." (PMID 32127798, 2020). "Further verification revealed that, similar with MEX3A, CDK6 was also upregulated in ESCC tumor tissues compared with normal tissues, which was also in consistent with the previous report." (PMID 33188661, 2020). "CDK6 is an upstream regulatory element of nuclear factor of activated T cells (NFAT), and CDK4/6 inhibitors suppress NFAT phosphorylation, the activation of CTLs, and its ability to kill tumor cells." (PMID 32357912, 2020). "In conclusion, MEX3A was identified as a tumor promotor in the development and progression of ESCC by targeting CDK6, which may be considered as a novel prognostic indicator and therapeutic target in treatment of ESCC." (PMID 33188661, 2020). "Moreover, we detected 15 gene amplifications in six different tumor specimens, including AR, CCND1 (n = 2), FGF19 (n = 2), FGF3 (n =2), KRAS (n = 2), MYC (n = 2), CCND3, CCNE1, CDK6, and RICTOR." (PMID 33203166, 2020). "Furthermore, safranal-treated tumor tissues exhibited a reduction in Skp2, E2F1, NF-κB p65, p-IκBα (Ser32), c-MYC, p-Rb (Ser807), CDK4, CDK6, and CDK2 and an elevation of p27 and p21 protein levels." (PMID 33392189, 2020). "In addition, the IHC results indicated that CDK6 expression increased in tumor-bearing tissues formed by SNHG17-overexpressing OVCAR-3 cells and decreased in tumor-bearing tissues formed by the SNHG17-knockdown OVCAR-3 cells." (PMID 32911343, 2020). "Irrespective of the shRNA mediated knockdown of CDK4 or CDK6 we failed to observe differences in the initial reaction to tumor cell injection; subcutaneous tumor nodules were readily visible." (PMID 30858922, 2019). "MYCN copy number alteration (amplification) was seen in one tumor while CDK6 amplification was not seen." (PMID 29869738, 2018). "We performed RT-PCR analysis for CDK6 and CCND3 on these tumor masses." (PMID 28114995, 2017). "Additionally, in vivo abemaciclib leads to a substantial reduction in tumor volume through downregulation of CDK4, CDK6, Cyclin D, Rb1, and E2F1 gene expression." (PMID 29245989, 2017). "Promotes tumor growth and cell cycle progression in LSCC by regulating the miR-107/CDK6 pathway." (PMID 27802187, 2017). "Many of these genes, including those encoding bFGF, MAPK10, MAP3K5, IL1R2, E-cadherin, Ki67, Cyclin E1, beta-catenin, 14-3-3 protein T-cell (YWHAQ), integrin alpha-V (ITGAV), integrin alpha-10 (ITGA10), CDK6, PCNA, CDKN1A, and PAK3, are related to tumor metastasis and regulation of cell migration." (PMID 28454092, 2017). "Interestingly, many of these genes are known to be involved in cell-cycle function (CDK2, CDK6, CCNB1, CEP55, CENPF), transcriptional regulation/tumor suppression (FOXO3, TOP2A), DNA-damage response (ASPM, XRCC4), and tumor progression (CYR61, MACC1, CXCR4)." (PMID 28482906, 2017). "In addition, the tumor suppressor miR-125a, which targets ERBB2 (erb-b2 receptor tyrosine kinase 2), and miR-129, which targets CDK6 (cyclin-dependent kinase 6), are also involved in anti-proliferative and pro-apoptotic functions." (PMID 27322246, 2016). "None of the new chimeric mice showed accelerated tumorigenesis or higher incidence of tumors, yet 3 of 4 tumors harboring CDK14 or CDK14/CDK6/FZD1 were easily propagated, strongly suggesting that overexpression of CDK6 and CDK14 are important for ectopic tumor growth and metastasis." (PMID 25162504, 2014).
tumor (continued). "Comparison of the genome of this tumor, CB42, with genomes from non-propagating tumors by array CGH and sequencing revealed an amplicon on chromosome five containing CDK6 and CDK14, and a KRAS mutation, respectively." (PMID 25162504, 2014). "CDK6 is not the only factor that promotes blood vessel growth, but it contributes substantially to meeting the tumor’s enhanced demand for blood supply." (PMID 23948297, 2013). "These experiments confirm that the tumor-suppressing effect of high CDK6 expression results from a negative feedback loop mediated by p16INK4a." (PMID 23948297, 2013). "A third miRNA downregulated by c-Myc is the tumor suppressor let-7 miRNA cluster, which targets, among others, the Ras oncogene, HMGA2 (high mobility group A2), Bcl-XL, Cdc25A, CDK6 (cyclin-dependent kinase 6), and cyclin D2." (PMID 23431463, 2013). "Our data showed that although expression of cdk-4, cdk-6, and p27 was not affected by sorafenib, the levels of cyclin D1, cyclin cdk-2, and cyclin B1 in sorafenib-treated tumours were significantly reduced as compared with controls (P<0.05)." (PMID 21407223, 2011). "We hypothesize that miRNAs that show significant up- or downregulation in GPs may regulate the expression of genes that are involved in the cell cycle (AURKB, CDC45, and CDK6), cell proliferation (EGFR and VEGFA), and angiogenesis (VEGFA) that support tumor growth." (PMID 40143207, 2025). "The tumor tissues were then analyzed by Western blotting to detect the different expression levels of proliferation (Ki67 and PCNA), apoptosis (c-Casp3, c-PARP), metastasis (vimentin), related substrate (p-PDH, HDAC1), and cell cycle-related proteins (CDC25A, CDK4, CDK6, and Rb) in each group." (PMID 38948069, 2024). "The α-helix face of its ANK structural domain and the intermediate β-hairpin together bind the C-termin and N-termin of CDK6, locking the kinase in a conformation that is not conducive to activation, thereby regulating the cell cycle and exerting a tumor suppressor function." (PMID 37277814, 2023). "However, the tumor tissues in the GAA treatment group and the combination group showed lower levels of LRPPRC and CDK6 than the control group and CDK4/6i monotherapy group, suggesting that the addition of GAA can also block the LRPPRC-CDK6 feedback loop in vivo." (PMID 37452037, 2023). "Along with the activation of JNK signalling in tumour without CDK6 amplification with combination therapy, the absence of ERK signal further reflects the transition to an endocrine independent resistance state, with reduced reliance on the interaction of ESR1/ERK." (PMID 35800379, 2022). "Interestingly, molecular analysis review conducted on tumor samples with the new v12.3 classifier showed a match with pediatric RTK1 type, subtype B, and a complex copy number variation (CNV) with CDK6 and MET amplification, and a platelet-derived growth factor A (PDGFRA) gain." (PMID 35204463, 2022). "Our study revealed a potential tumor-suppressive role of miR-500a-3p in CRC, specifically targeting CDK6 and inhibiting cancer cell proliferation and aerobic glycolysis, which may provide new insights into novel prognostic biomarkers and therapeutic targets for CRC." (PMID 35241106, 2022). "In conclusion, our findings in the study confirmed that miR-34a overexpression could simultaneously suppress tumor growth and metastasis and play a vital role in tumorigenesis and progression of NSCLC via increasing PTEN and YY1 expression, but decreasing CDK6." (PMID 33796457, 2021). "Compared with that in normal tissue, CDK4/6 mRNA expression was remarkably higher in tumor tissue overall, which demonstrated that CDK4/6 are abnormally expressed in multiple tumors; however, there was no significant change in some levels between normal tissue and tumor tissue, including CDK6 in OC." (PMID 35095879, 2021).